DYSF (dysferlin)
Diseases named in the same sentence as DYSF in open-access papers (continued):
Sharing a sentence is not in itself a finding about the gene and the disease.
dysferlinopathy (continued). "In patients suffering from dysferlinopathies, a large variety of mutations has been identified in the DYSF gene, which is located on chromosome 2p12-14." (PMID 34067866, 2021). "Dysferlinopathies are a group of muscular dystrophies caused by recessive mutations in the DYSF gene encoding the dysferlin protein." (PMID 34888307, 2021). "Dysferlinopathies are disabling muscle disorders caused by recessive mutations in the DYSF gene (MIM# 603009, 2p13, GenBank NM_003494.3) encoding the dysferlin protein." (PMID 34888307, 2021). "Dysferlinopathies are a group of muscle disorders caused by mutations to dysferlin, a transmembrane protein involved in membrane patching events following physical damage to skeletal myofibers." (PMID 34366880, 2021). "Dysferlinopathies are caused by mutations in dysferlin and include a spectrum of muscle disease characterized by two main phenotypes, MMD and limb-girdle muscular dystrophy type 2B (LGMD2B)." (PMID 34276779, 2021). "In this experiment, we utilized the iPSC line CiRA00396 derived from a patient with Miyoshi myopathy (a form of dysferlinopathy), who has a homozygous recessive nonsense mutation of c.C3166T (p.Arg1056Ter) at exon 29 in the Dysferlin (DYSF) gene." (PMID 33711268, 2021). "This study aimed to expand the mutational spectrum of dysferlinopathies, to further study one case with diagnostic ambiguity, and to identify the diagnostic value of dysferlin expression in total peripheral blood mononuclear cells (PBMC)." (PMID 33613410, 2020). "To study the possible role of Cx HCs in dysferlinopathy, we used boldine as a potential therapeutic drug, in dysferlin deficient myoblasts, and in blAJ mice, the animal model of dysferlinopathies." (PMID 32825681, 2020). "Skeletal muscles develop normally in pre-symptomatic dysferlinopathy patients and dysferlin-deficient mice." (PMID 32106631, 2020). "The dysferlin-deficient mice (dysf-/-) replicate well human dysferlinopathies, showing similarities with the human condition although with milder histopathological aspects." (PMID 33255644, 2020). "On the protein level, dysferlinopathies are diagnosed by a complete loss or severe reduction of dysferlin in muscle biopsies or peripheral blood monocytes." (PMID 32106631, 2020). "Signs of oxidative stress have been observed in skeletal muscles of dysferlinopathy patients, as well as in dysferlin-deficient mice." (PMID 32560255, 2020). "Dysferlinopathies are a group of autosomal recessive muscular dystrophies caused by mutations in the gene encoding dysferlin, a highly expressed skeletal muscle protein critical for sarcolemma repair." (PMID 32560255, 2020). "Studies in the muscle of both human and mouse models of dysferlinopathy suggest dysferlin deficient muscle plays a role in this inflammation by releasing thrombospondin-1." (PMID 33246442, 2020). "Dysferlinopathies are muscle dystrophies caused by mutations in the gene encoding dysferlin, a relevant protein for membrane repair and trafficking." (PMID 32825681, 2020). "Surprisingly, patients with dysferlinopathies caused by mutations in DYSF genes present frequently mitochondrial complex I and IV deficiencies." (PMID 32575867, 2020). "The higher (96%) homozygosity rate of pathogenic variant in DYSF gene explains why autosomal recessive disorders like dysferlinopathy are more common in the Indian subcontinent." (PMID 33250842, 2020). "The aim of this study was to define the DYSF mutational and phenotypic spectra in Chinese dysferlinopathies." (PMID 33613410, 2020). "Dysferlinopathy is an autosomal recessive muscular dystrophy resulting from mutations in the dysferlin gene." (PMID 32560255, 2020). "Dysferlinopathies are a group of muscle disorders causing muscle weakness and absence or low levels of dysferlin, a type-II transmembrane protein and the causative gene of these dystrophies." (PMID 33246442, 2020).
dysferlinopathy (continued). "Dysferlinopathies are a heterogenous group of progressive muscular dystrophies characterized by mutations in the DYSF gene, leading to reduced or null expression of the dysferlin protein and resulting in varied phenotypes." (PMID 33240103, 2020). "Here, we analyzed the redox status of two skeletal muscles, quadriceps and gastrocnemius, in dysferlin-deficient Bla/J mice, a dysferlinopathy animal model." (PMID 32560255, 2020). "Mutations in DYSF (dysferlin) can cause a range of muscle diseases with various clinical manifestations collectively known as dysferlinopathies, including limb-girdle muscular dystrophy type 2B (LGMD2B) and Miyoshi myopathy." (PMID 32106631, 2020). "In summary, this study presents novel DYSF mutations in a group of Chinese patients and expands the phenotypic spectrum of dysferlinopathies." (PMID 33613410, 2020). "Dysferlinopathy is an autosomal recessively inherited form of muscular dystrophy caused by mutations in the DYSF gene." (PMID 33391171, 2020). "Mutations in the dysferlin gene (DYSF) that lead to absence or marked reduction of the protein are the cause of dysferlinopathy." (PMID 33246442, 2020). "Dysferlinopathies are a clinically heterogeneous group of muscle disorders that arise from mutations in the dysferlin gene (DYSF) that reduce expression of functional dysferlin protein." (PMID 30970035, 2019). "DYSF deficiency causes dysferlinopathy and leads to defective membrane resealing in skeletal muscle and to muscle necrosis." (PMID 31601172, 2019). "Dysferlinopathies are a form of muscular dystrophy caused by gene mutations resulting in deficiency of the protein dysferlin." (PMID 30970035, 2019). "As expected, skeletal muscle cells derived from dysferlinopathy patients and dysferlin-deficient mice display a defective Ca2+-dependent plasmalemma repair." (PMID 31861684, 2019). "Mutations in the dysferlin gene cause a group of autosomal recessive muscular dystrophies known as dysferlinopathies." (PMID 31861684, 2019). "Dysferlin-deficient Bla/J mice (one of the models of dysferlinopathy) are also characterized by impaired lipid metabolism." (PMID 30823359, 2019). "Studies of dysferlin-deficiency typically use dysf-/- mice as they have similar muscle structure to humans and more accurately represent the disease pathology in human dysferlinopathies, compared with dysf-/- zebrafish, roundworm and fruit fly." (PMID 30970035, 2019). "Another case of a bent spine syndrome/camptocormia, presenting in the seventh decade, appears to be an unusual presentation of pauci-symptomatic dysferlinopathy based on a heterozygous dysferlin mutation." (PMID 29879922, 2018). "A definitive diagnosis of dysferlinopathy can only be made when pathogenic mutations are identified in the large (>233Kbp, 58 exons, >6Kbp coding sequence) dysferlin (DYSF) gene, which lacks mutation hotspots." (PMID 29879922, 2018). "Our finding of a truncating dysferlin mutation confirmed dysferlinopathy in this family and we propose that the single mutant allele is the primary contributor to the neuromuscular symptoms seen in the second-generation pauci-symptomatic carriers." (PMID 29879922, 2018). "The identification of a dysferlin‐deficient animal model that accurately displays both the physiological and behavior aspects of human dysferlinopathy is critical for the evaluation of potential therapeutics." (PMID 28320887, 2017). "We compared these with biopsies from a same-aged healthy subject (control) and from patients with muscular dystrophy caused by mutations in the dysferlin gene (dysferlinopathy) or in the dystrophin gene (dystrophinopathy)." (PMID 28676641, 2017). "Dysferlinopathy is an autosomal recessive disease covering a wide spectrum of phenotypes caused by different mutations in the DYSF gene which encodes dysferlin." (PMID 28134780, 2017). "These entities are grouped as dysferlinopathies and are caused by mutations in the dysferlin gene on chromosome 2p13." (PMID 28219397, 2017).
dysferlinopathy (continued). "Mutations in the gene encoding for dysferlin cause recessive autosomal muscular dystrophies called dysferlinopathies." (PMID 27229680, 2016). "Dysferlin is a protein considered to function in Ca2+-dependent membrane repair in muscles, and mutations in its gene cause dysferlinopathies, including limb girdle muscular dystrophy type 2B and Miyoshi myopathy (21, –, 23)." (PMID 27303688, 2016). "Mutations in this domain of the dysferlin protein cause dysferlinopathies, including limb girdle muscular dystrophy type 2B and Miyoshi myopathy (20, –, 23), although the precise function of the domain is not known." (PMID 27303688, 2016). "Dysferlinopathy is characterized by the loss (or significant reduction to <10% normal levels) of the dysferlin protein (encoded by the DYSF gene) in the skeletal muscle of affected patients and has an autosomal recessive mode of inheritance." (PMID 27195159, 2016). "Dysferlinopathies are muscular dystrophies caused by mutations in dysferlin, a 230 kDa membrane protein, mainly localized in the sarcolemma and the T-tubule system." (PMID 27229680, 2016). "Loss-of-function mutations in the dysferlin gene (DYSF) result in a family of muscle disorders known collectively as the dysferlinopathies." (PMID 26251696, 2015). "Recessive core myopathies, where the skeletal muscle Ryanodine receptor gene (RYR1) is mutated, and dysferlinopathies, caused by mutations in Dysferlin (DYSF) gene, show a percentage of patients with only an identified mutated allele." (PMID 25798107, 2015). "Mutations in DYSF gene are known to cause a range of autosomal recessive myopathies, called dysferlinopathies including Miyoshi myopathy and limb girdle muscular dystrophy type 2B (LGMD2B)." (PMID 24948216, 2014). "Dysferlinopathies are a group of autosomal recessive inherited late onset progressive muscular dystrophies caused by malfunction of dysferlin protein." (PMID 24438169, 2014). "Mutations in dysferlin, the first protein linked with the cell membrane repair mechanism, causes a group of muscular dystrophies called dysferlinopathies." (PMID 24438169, 2014). "Dysferlinopathy arises from mutations in the dysferlin gene, which contains 55 exons and spans a region of 150 kb." (PMID 23406536, 2013). "Dysferlinopathies are autosomal recessive muscular dystrophies caused by mutations in the gene encoding dysferlin (DYSF; Online Mendelian Inheritance in Man [OMIM] gene number 603009, Chr 2p13, GenBank NM_003494.2)." (PMID 23406536, 2013). "Dysferlinopathies are autosomal recessive disorders caused by mutations in the dysferlin (DYSF) gene encoding the dysferlin protein." (PMID 23406536, 2013). "The dysferlinopathies are a category of muscular dystrophy arising due to mutations in the dysferlin (DYSF) gene." (PMID 25562650, 2013). "Limb-girdle muscular dystrophy 2B (LGMD2B) is the most prominent dysferlinopathy caused by mutations in the dysferlin (DYSF) gene." (PMID 23185377, 2012). "LGMD2B is a typical phenotype of dysferlinopathy caused by mutations in DYSF." (PMID 41517735, 2026). "Mutations in the DYSF gene cause a progressive muscle-wasting disease called dysferlinopathy." (PMID 41584851, 2026). "Moreover, both CAPN3 and dysferlin are closely associated with the Cav1.1–RyR complex, and in dysferlinopathy models, the Ca leak can be attenuated by dantrolene." (PMID 41357548, 2025). "Pathogenic variants associated with the disease have been identified in all exons of the DYSF gene, and, due to the variant-specific nature of exon skipping strategies, each exon skipping strategy would only be applicable to a subset of the dysferlinopathy patient population." (PMID 39936969, 2025). "In fact, mutations in human DysF protein linked to dysferlinopathies are mostly in the DysF domain." (PMID 40407416, 2025). "CAPN3 gene mutations may contribute to dysferlinopathy symptoms, and dysferlin may act as a modifier gene in calpainopathies." (PMID 38540676, 2024).
dysferlinopathy (continued). "An earlier study identified increased susceptibility to complement attack due to down-regulation of DAF1/CD55 and DAF2/CD55b only in dysferlin-deficient muscles, demonstrated by mRNA and protein analyses in dysferlin-deficient mouse models and patients with dysferlinopathy." (PMID 39123261, 2024). "We give a brief update on clinical trials involving adeno-associated viral gene therapy and the current progress on CRISPR/Cas9 mediated therapy for LGMD2B, and then conclude by discussing the prospects of antisense oligomer-based intervention to treat selected mutations causing dysferlinopathies." (PMID 38891760, 2024). "We recognise that these are preliminary observations but they highlight new areas for study to (i) identify the mechanistic basis of dystropathology in dysferlin-deficient muscles and (ii) gain further insight into the unexpected adverse effects of GCs in dysferlinopathy." (PMID 39123261, 2024). "from Massachusetts General Hospital, uncovered the DYSF gene associated with dysferlinopathies." (PMID 38540676, 2024). "Variants in DYSF can lead to dysferlinopathy, a subgroup of LGMD." (PMID 38539162, 2024). "Two homozygous adjacent missense mutations in the DYSF gene may be associated with the development of dysferlinopathy, but the exact mechanism needs further investigation." (PMID 38903757, 2024). "Genetic testing for DYSF mutations is the gold standard for clinical diagnosis, and Western blot testing for dysferlin deficiency in monocytes, combined with clinical manifestations, can also diagnose dysferlinopathy." (PMID 38903757, 2024). "Nowadays, there are three drugs in research pipelines using this approach for ABCA4‐associated Stargardt diseases, dysferlinopathy associated with the DYSF gene, Usher syndrome type 2 B caused by mutations in MYO7A gene and hearing loss due to OTOF malfunction." (PMID 38488469, 2024). "These phenotypes have not been reported in the previous literature, and this mutation may provide evidence of a correlation between mutations in the DYSF gene and the dysferlinopathy phenotype." (PMID 38903757, 2024). "The results indicated that the two homozygous mutations in the DYSF gene affected splicing function and may be one of the causes of dysferlinopathy." (PMID 38903757, 2024). "Dysferlinopathies are a heterogeneous class of autosomal recessive muscular dystrophies that arise from mutations in the dysferlin (Dysf) gene, causing deficiency of the dysferlin protein." (PMID 39123261, 2024). "Dysferlinopathies represent a group of limb girdle or distal muscular dystrophies with an autosomal recessive inheritance pattern resulting from the presence of pathogenic variants in the dysferlin gene (DYSF)." (PMID 38235354, 2023). "It is unsurprising, given dysferlin’s role in the muscle sarcolemma, that numerous pathogenic mutations in the dysferlin gene are linked to muscle wasting diseases known collectively as dysferlinopathies and attributable to failure of muscle repair mechanisms." (PMID 37025168, 2023). "Autosomal recessive variants in the DYSF gene, encoding dysferlin, give rise to dysferlinopathy." (PMID 36653852, 2023). "Dysferlinopathy is a disease caused by a dysferlin deficiency due to mutations in the DYSF gene." (PMID 37762951, 2023). "Thus, molecular analysis of the genes associated with dysferlinopathy or estimation of the presence of dysferlin protein is a very useful approach for distinguishing dysferlinopathy from other muscular disorders." (PMID 36672942, 2023). "The precise pathogenic mechanism underlying dysferlinopathy remains unclear; it is hypothesized that defective membrane repair in dysferlin-deficient muscle leads to muscular dystrophy associated with remarkable muscle inflammation." (PMID 38125829, 2023). "Recessive variants in DYSF result in dysferlinopathy, a progressive muscular dystrophy." (PMID 36653852, 2023).
dysferlinopathy (continued). "Consequently, two pathogenic single nucleotide variants of the DYSF gene, c.663 + 1G > C (rs398123800) and p.Trp992Arg (rs750028300), associated with dysferlinopathy were identified." (PMID 36672942, 2023). "This is especially true for autosomal recessive conditions such as dysferlinopathy, since the identification of two pathogenic variants in DYSF can be challenging due to the large number of rare DYSF variants identified and the difficulty in determining pathogenicity." (PMID 36983702, 2023). "As we recently reported, quadriceps and gastrocnemius muscles of dysferlin-deficient Bla/J mice, another model of dysferlinopathy, exhibit high levels of protein oxidation and lipid peroxidation and altered activity of the antioxidant enzymes superoxide dismutase and catalase." (PMID 35203715, 2022). "In this regard, an additional function of dysferlin has been proposed, which could be implicated in the pathological mechanisms of dysferlinopathy." (PMID 35203715, 2022). "Patients with dysferlinopathy typically have dysferlin labeling loss in muscle biopsies." (PMID 36203997, 2022). "Thus, the main dysferlin dysfunction caused by dysferlinopathy-linked mutations requires further study." (PMID 35203715, 2022). "Finally, a relevant upregulation of oxidative stress and NFκB-signalling has been identified in dysferlinopathy (LGMD2B/LGMDR2), a muscular dystrophy arising from mutation in the DYSF-gene." (PMID 32823799, 2020). "In addition to skeletal muscle, dysferlin is expressed in other tissues, and the dysferlin expression level in blood monocytes can be used as a diagnostic tool for dysferlinopathy." (PMID 33613410, 2020). "In dysferlinopathies, almost all fibers are stained with antibodies against dystrophin 1, 2, and 3, merosin, β-spectrin, and α, β, and γ sarcoglycans; but the muscle fibers are looked completely deficient against dysferlin antibody." (PMID 31937337, 2020). "Dysferlinopathies are autosomal recessive muscular dystrophies caused by mutations in DYSF." (PMID 33613410, 2020). "Myoblasts isolated from dysferlinopathy patients or derived from dysferlin-deficient mice proliferated with the normal rate, but showed decreased fusion efficiency in vitro as a result of activated signaling of the pro-inflammatory network inhibiting myogenesis." (PMID 32106631, 2020). "Despite this correlation between increased dysferlin levels and polyol pathway activity, data obtained from dysferlin deficient mice and primary myoblasts from dysferlinopathy patients indicate certain similarities with the metabolic phenotype seen in our nerve damage model." (PMID 32024865, 2020). "Dysferlinopathies are diseases caused by mutations in DYSF, affecting mainly skeletal muscles." (PMID 32106631, 2020). "Another neuromuscular disorder is dysferlinopathy, induced by a deficiency of dysferlin protein." (PMID 30823359, 2019). "Dysferlinopathies are a group of muscle disorders caused by mutations in the DYSF gene." (PMID 29735511, 2018). "We confirm dysferlinopathy in this family due to a novel truncating p.Tyr1433Ter DYSF mutation." (PMID 29879922, 2018). "In both Chinese and Korean patients with dysferlinopathy, the mutations spanned the whole length of DYSF gene, although there was a trend that mutations clustered in the N-terminal region of DYSF gene, suggesting a possible common mutation hot spot in China and Korea." (PMID 28403181, 2017). "Our results suggest the possibility that fibroblasts can be used as a research tool for dysferlinopathy, and that proteasome inhibitor may be a potential treatment for dysferlinopathy patients harboring truncated or mis-sense mutated dysferlin." (PMID 26579332, 2015). "We reported that aged (~12 month) dysferlin-deficient murine muscle also exhibits amplified X-ROS signaling, a finding congruent with the recent reports suggesting that oxidative stress underscores the late onset and temporal progression of dysferlinopathy." (PMID 24600403, 2014).